SLC2A4 (solute carrier family 2 member 4)
Description:
Insulin-regulated facilitative glucose transporter, which plays a key role in removal of glucose from circulation. Response to insulin is regulated by its intracellular localization: in the absence of insulin, it is efficiently retained intracellularly within storage compartments in muscle and fat cells. Upon insulin stimulation, translocates from these compartments to the cell surface where it transports glucose from the extracellular milieu into the cell.
Synonyms: GLUT4
Tractability: Small molecule: a structure with a bound ligand is known. Antibody: its Gene Ontology location is reachable by antibodies, with high confidence; UniProt places it where antibodies can reach, with medium confidence; UniProt predicts a signal peptide or a membrane-spanning region. PROTAC: UniProt records ubiquitination sites on it; a small molecule that binds it is known.
Target class: SLC superfamily of solute carriers; Electrochemical transporter; SLC02 family of hexose and sugar alcohol transporters; Transporter
Gene: Protein-coding gene on chromosome 17 (7,281,667 to 7,289,241, forward strand). Ensembl gene ENSG00000181856.
Subcellular location: Cell membrane; Endomembrane system; Cytoplasm, perinuclear region
Pathways (Reactome):
Developmental Biology: Transcriptional regulation of white adipocyte differentiation
Transport of small molecules: Cellular hexose transport
Vesicle-mediated transport: Translocation of SLC2A4 (GLUT4) to the plasma membrane
Gene Ontology:
Molecular function: D-glucose transmembrane transporter activity; protein binding; D-glucose uniporter activity; transmembrane transporter activity
Biological process: cellular response to insulin stimulus; glucose homeostasis; carbohydrate metabolic process; D-glucose import across plasma membrane; D-glucose transmembrane transport; dehydroascorbic acid transport; glucose import in response to insulin stimulus; learning or memory; long-term memory; positive regulation of brain-derived neurotrophic factor receptor signaling pathway; short-term memory; transport across blood-brain barrier; white fat cell proliferation; cellular response to hypoxia; regulation of synaptic vesicle budding from presynaptic endocytic zone membrane; response to ethanol; transmembrane transport
Cellular component: clathrin-coated vesicle; endomembrane system; external side of plasma membrane; insulin-responsive compartment; perinuclear region of cytoplasm; plasma membrane; trans-Golgi network; vesicle membrane; cytoplasmic vesicle membrane; membrane; sarcolemma; cell surface; clathrin-coated pit; cytoplasm; cytosol; endosome; extracellular exosome; membrane raft; multivesicular body; presynapse; sarcoplasmic reticulum; T-tubule; trans-Golgi network transport vesicle; vesicle
Genetic constraint (gnomAD): Loss-of-function variants: 31 observed, 54.1 expected, observed/expected ratio (o/e) 0.57, 90% interval 0.43 to 0.77. The upper end of that interval is the gene's LOEUF score, 0.77, which puts it in group 3 of 6, group 1 being the genes least tolerant of losing a copy. Missense variants: 537 observed, 678.05 expected, observed/expected ratio (o/e) 0.79, 90% interval 0.74 to 0.85. Synonymous variants: 276 observed, 290.15 expected, observed/expected ratio (o/e) 0.95, 90% interval 0.86 to 1.05.
Homologues: Orthologues: macaque SLC2A4 (97% identical), mouse Slc2a4 (95% identical), rat Slc2a4 (95% identical), pig SLC2A4 (95% identical), guinea pig SLC2A4 (94% identical), rabbit SLC2A4 (91% identical), chimpanzee SLC2A4 (88% identical), dog SLC2A4 (75% identical), tropical clawed frog slc2a4 (68% identical), Drosophila melanogaster sut1 (34% identical), Drosophila melanogaster CG7882 (32% identical), Caenorhabditis elegans fdgt-1 (31% identical), and 39 more. Paralogues in human: SLC2A1 (63% identical), SLC2A3 (56% identical), SLC2A14 (55% identical), SLC2A2 (53% identical), SLC2A5 (41% identical), SLC2A7 (38% identical), SLC2A9 (37% identical), SLC2A11 (34% identical), SLC2A13 (29% identical), SLC2A12 (27% identical), SLC2A8 (26% identical), SLC2A6 (25% identical), and 1 more.
Diseases named in the same sentence as SLC2A4 in open-access papers:
SLC2A4 is named in the same sentence as 219 diseases in open-access papers, as found by Europe PMC text mining. Sharing a sentence is not in itself a finding about the gene and the disease. The quoted sentences say what the papers report.
Insulin resistance (1,218 papers, 2001 to 2026). Increased resistance towards insulin, that is, diminished effectiveness of insulin in reducing blood glucose levels. "Further molecular analysis demonstrated that the loss of RNF20 reduced H3K4me3 modifications at the Slc2a4 gene locus, thereby decreasing its expression and ultimately contributing to the development of insulin resistance." (PMID 40522008, 2025). "We identify a common intronic variant (rs117643180) in SLC2A4 to be associated with post-challenge insulin resistance and demonstrate it’s in silico and in vitro effect on SLC2A4 expression in skeletal muscle." (PMID 37291194, 2023). "These functions are related to insulin resistance due to reduced insulin binding, downregulation of GLUT4 (encoded by SLC2A4), diminished glucose transport in skeletal muscle and adipose tissue, as well as insulin-induced gluconeogenesis in the liver." (PMID 34884524, 2021). "It was shown that age-related reduction of expression the Glut4 encoding gene, slc2a4, is associated with the development of decreased glucose tolerance and insulin resistance." (PMID 31893310, 2020). "Impaired regulation of SLC2A4 gene expression and function is associated with insulin resistance and conditions such as type 2 diabetes and obesity in humans and equines." (PMID 30250736, 2018). "Obesity is associated with insulin resistance and reduced Slc2a4/GLUT4 expression in both muscle and fat." (PMID 25834641, 2015). "Decreased expression of glucose transporter protein GLUT4, encoded by the solute carrier 2A4 (Slc2a4) gene, is involved in obesity-induced insulin resistance." (PMID 25834641, 2015). "Insulin resistance in 7CafD females was associated with a reduced expression of insulin signalling and glucose transport genes in all metabolic tissues: Insr and Irs2 in liver, Insr and Slc2a4 in WAT, and Slc2a4 in muscle." (PMID 39596499, 2024). "Indeed, we found that DNA methylation is dynamically altered and associated with reciprocal Slc2a4 expression and fatty acids in obese humans and mice with insulin resistance." (PMID 37047391, 2023). "Indeed, while the knockout of the Slc2a4 gene, which encodes GLUT4 protein, results in insulin resistance, its overexpression ameliorates diabetes." (PMID 29609616, 2018). "Polymorphisms in the SLC2A4 gene encoding the glucose transporter 4 (GLUT4), have been linked to insulin resistance and T2D." (PMID 40854653, 2025). "Mechanistically, Rnf20 knockdown in adipocytes reduced H3K4me3 occupancy at the Slc2a4 gene locus, inhibiting GLUT4 expression and inducing adipose‐specific insulin resistance." (PMID 40522008, 2025). "In fact, inflammatory cytokines are well documented for their involvement in lowering SLC2A4 levels and increasing insulin resistance." (PMID 40149869, 2025). "GLUT4 is usually found only in insulin-sensitive skeletal muscle and adipocytes, and decreased SLC2A4 expression or GLUT4 activity can cause insulin resistance." (PMID 39850557, 2024). "SLC2A4 or GluT4 participates in cognitive impairment, its production is reduced due to insulin resistance that also occurs in DM2." (PMID 36778155, 2023). "The solute carrier family 2 member 4 (SLC2A4) gene, encoding for the insulin-dependent glucose transporter type 4 (GLUT4) in muscle and adipose tissue, has therapeutic potential for the treatment of insulin resistance in obesity and in specific cancer types." (PMID 37047391, 2023). "In diet-induced obese (DIO) mice, DNA methylation of Slc2a4 persistently increases with the onset of obesity and insulin resistance, while gene expression progressively decreases." (PMID 37047391, 2023). "While the translocation of the GLUT4 protein in white adipose tissue (WAT) is impaired in insulin resistance, SLC2A4 expression is already decreased in the proceeding obese state." (PMID 37047391, 2023).
Insulin resistance (continued). "Animal studies revealed the mechanism of action for osteocalcin in the amelioration of insulin resistance by decreasing inflammation and improving insulin signaling in white adipose tissue over the expression of Slc2a4/GLUT4." (PMID 35010988, 2021). "In view of that, we have continued to focus our studies on the regulation of the SLC2A4 gene, considering it a promising target for the pharmacogenomics of insulin resistance." (PMID 33430527, 2021). "SLC2A4 global-deficient mice exhibited fasting hyperglycemia and glucose intolerance, while overexpression of SLC2A4 in adipose tissue resulted in alleviating insulin resistance." (PMID 30239845, 2019). "Recently, we have reported the participation of inflammation in insulin resistance by showing that the nuclear factor kappa B (NFKB) downregulates specifically the Slc2a4 gene." (PMID 29609616, 2018). "Another miRNA confirmed as a direct regulator of Slc2a4/GLUT4 is the miR-223-3p, which has been described as upregulated in adipose tissue of women with insulin resistance." (PMID 28428964, 2017). "In fact, Slc2a4 gene becomes a promising target for pharmacogenomics of insulin resistance, and, for that, it is mandatory to unravel mechanisms related to the SLC2A4 gene expression, such as its epigenetic regulation by microRNAs." (PMID 28428964, 2017). "The present data clearly show that obese mice developed insulin resistance which was accompanied by reduced Slc2a4 mRNA and protein content in SAT." (PMID 25834641, 2015). "Abnormal expression of SLC2A4 was reported in patients who were diagnosed with obesity, insulin resistance and liver dysfunction." (PMID 26442469, 2015). "Obese mice showed insulin resistance, decreased expression of Slc2a4 mRNA (66%, P < 0.01) and GLUT4 protein (30%, P < 0.05), and increased expression of interleukin 6 (Il6) mRNA (44%, P < 0.05) in SAT." (PMID 25834641, 2015). "In vitro, the GA-induced repression of Slc2a4/GLUT4 expression was first reported in muscle, but now it is described to occur in adipocytes, the effects of which can lead to participation in insulin resistance and thus contribute to inducing DM and/or worsening pre-existing DM." (PMID 39125811, 2024). "Indeed, in 12-week-treated healthy rats with AGE-albumin, insulin resistance was observed, accompanied by the reduced expression of Slc2a4/GLUT4 in both adipose and skeletal muscle tissues." (PMID 39125811, 2024). "Also, in another study, they showed that epigenetic modifications play a role in insulin resistance through decreasing the expression of Solute carrier family-2-member-4 (Slc2a4) gene." (PMID 38027557, 2023). "Insulin resistance in women with GDM can also be a result of imperfect SLC2A4 translocation." (PMID 38068941, 2023). "We hypothesize that increased DNA methylation in an enhancer region of Slc2a4 decreases Slc2a4 expression in obesity and insulin resistance." (PMID 37047391, 2023). "Herewith, we describe a novel epigenetic mechanism regulating the SLC2A4 gene by fatty-acid-induced alterations in DNA methylation, which may play a role in the development of insulin resistance in obesity." (PMID 37047391, 2023). "Using this approach, we identified 9 loci not previously associated with post-challenge insulin resistance in studies of European ancestry, including SLC2A4, which encodes the glucose transporter implicated in insulin-stimulated glucose disposal." (PMID 37291194, 2023). "For example, it may be that aberrant GLUT4 traffic and localisation, as observed in insulin resistance, leads to increased GLUT4 turnover or decreased Glut4/Slc2a4 expression." (PMID 36283703, 2023). "hypothesized that the decrease of SLC2A4 in endometrium would lead to endometrial insulin resistance and may damage endometrial metabolism." (PMID 33343510, 2020).
Insulin resistance (continued). "After further studying whether metformin could improve endometrial insulin resistance, they found that the expression of SLC2A4 mRNA and protein in obese PCOS patients was significantly lower than that in obese non-PCOS patients." (PMID 33343510, 2020). "High plasma NEFA levels are the hallmark of insulin resistance in that, elevated NEFA can block the action of the glucose transporter SLC2A4 which may explain the lower expression of SLC2A4 observed in the inefficient animals in the current study." (PMID 30250736, 2018). "Besides, participation of reduced skeletal muscle glucose disposal in the whole-body insulin resistance was evinced by the repression of Slc2a4 mRNA and GLUT4 protein expression." (PMID 29802324, 2018). "In vivo, AGE-albumin induced whole-body insulin resistance; decreased (~30%) Slc2a4 mRNA and GLUT4 protein content; and increased (~30%) the nuclear content of nuclear factor NF-kappa-B p50 subunit (NFKB1), and cellular content of 78 kDa glucose-regulated protein (GRP78)." (PMID 29802324, 2018). "On the other hand, OCN could improve insulin resistance by decreasing inflammation and promote insulin signaling as well as the expression of Slc2a4/GLUT4." (PMID 30186852, 2018). "The down-regulated expression of GCK and up-regulated expression of IGFBP1, PPARGC1A and SLC2A4 may indicate obesity and insulin resistance in rhesus models of liver steatosis." (PMID 26442469, 2015). "Atorvastatin treatment improves insulin resistance which may be related to its positive impact on Il6 and Slc2a4/GLUT4 expression in SAT." (PMID 25834641, 2015). "However, whether overexpression of the Slc2a4 gene in RNF20 knockdown cells could alleviate insulin resistance remains to be investigated, which would better elucidate the role of RNF20 in insulin signalling via Slc2a4 regulation." (PMID 40522008, 2025). "Curiously, in contrast to other vertebrates neither SLC2A4 mRNA nor GLUT4 protein were detected in birds and this absence was causally connected to the fact that birds have severe insulin resistance and relatively high blood glucose levels when compared to human standards." (PMID 34537008, 2021). "Furthermore, we and other researchers have extensively reported in the literature that conditions coursing with decreased expression Slc2a4 are accompanied by insulin resistance, whereas treatments that increase Slc2a4 expression are accompanied by the improvement of glycemic control." (PMID 33430527, 2021). "Diabetes and insulin resistance have been shown to present with hyperglycaemia and impaired insulin-sensitive glucose transporter (SLC2A4/GLUT4) translocation to the plasma membrane and a reduced expression in the rat heart." (PMID 40759793, 2025). "The NF-κB p65 directly induces insulin resistance by repressing the transcription of glucose transporter GLUT4 protein, codified by Slc2a4 gene in skeletal muscles by binding to the Slc2a4 gene promoter." (PMID 35454131, 2022). "Key down-regulated genes (i.e., CREB5, SLC2A4, SREBF1, CYP1A1, CHARD and COMP) are related to insulin resistance, response to virus infection, AMPK signalling and ECM receptor interaction (Table A6)." (PMID 34830490, 2021). "In summary, the data reveal that short-term exposition of muscle cells to palmitate can repress Slc2a4/GLUT4 expression, in a ER- and inflammatory-stress mediated way; thus, contributing to induce insulin resistance." (PMID 29609616, 2018). "In concert with the data obtained in our rodent models of obesity and insulin resistance, adipose tissue expression of other lipogenic genes, including PPARG, FASN, and SLC2A4, was lower in subjects with MAO than those with MNO." (PMID 29853530, 2018). "On the other hand, atorvastatin was able to restore Slc2a4 mRNA and protein content not only in VAT, but also in SAT of OB, contributing for amelioration of insulin resistance." (PMID 25834641, 2015).
Insulin resistance (continued). "Among them, GLUT4 (SLC2A4) is a dynamic modulator of normal glucose homeostasis in adipose and muscle tissues, and dysfuntion of GLUT4 leads to insulin resistance and type 2 diabetes." (PMID 26675316, 2015). "Specifically, there were quantitative differences between the expressions of IRS1, PIK3R1, SLC2A1, SLC2A3, and SLC2A4 among the patients with GDM during pregnancy and at 1-year postpartum, i.e., in the two studied groups differing in the degree of insulin resistance." (PMID 39684804, 2024). "Four of these loci, all not previously implicated in post-challenge insulin resistance, were significantly associated with IFC (N = 52,474; SLC2A4, PPP1R3B, C2CD4A and MTNR1B)." (PMID 37291194, 2023). "The remaining loci were associated with ISI, including 6 loci not previously implicated in post-challenge insulin resistance: MTOR, COBLL1, PPARG, C5orf67, FAM101A, SLC2A4." (PMID 37291194, 2023). "We hypothesized that an obesogenic diet, i.e., high fat content, induces DNA methylation of the glucose transporter 4 gene SLC2A4 in VAT of obese subjects and that this epigenetic dysregulation leads to insulin resistance by reduced SLC2A4 gene expression." (PMID 37047391, 2023). "On the other hand, glucose transporter 4 (GLUT4), which is coded by the SLC2A4 gene, is the center of most studies on insulin resistance, since it is the major means of glucose transport in insulin-sensitive peripheral tissues (i.e., skeletal muscles and adipose tissues)." (PMID 34360895, 2021). "On the other hand, we observed an increase in SLC2A4 expression in VAT-derived adipocytes, which may be a compensatory effect of newly developed insulin resistance." (PMID 32962087, 2020). "Therefore, it can be assumed that the reduction of Slc2a4/GLUT4 expression in both SAT and VAT contributes to the whole-body insulin resistance in this animal model of obesity." (PMID 25834641, 2015). "Furthermore, has a suppressive impact on protein phosphatase activity and participates in lipid metabolism and insulin resistance, however, in avian skeletal muscle insulin does not affect muscle glucose transport, mainly due to the lack of the SLC2A4 gene." (PMID 38717527, 2024). "Since the characterization of GLUT4, and considering its central role in glycemic homeostasis, several studies have been performed attempting to understand the role of the skeletal muscle SLC2A4/GLUT4 expression and translocation in the pathophysiology of insulin resistance and/or diabetes." (PMID 28428964, 2017). "Interestingly, insulin resistance prevented by NAC, which was also able to reduce lipid peroxidation (TBARS), adipose tissue macrophages (total number and M1 and M2 markers, respectively, Itgam and Mrc) and to enhance Slc2a4, Ppara in adipose tissue." (PMID 29018354, 2017).